KHDRBS1 (KH RNA binding domain containing, signal transduction associated 1)
Diseases named in the same sentence as KHDRBS1 in open-access papers (continued):
Sharing a sentence is not in itself a finding about the gene and the disease.
tumor (continued). "Furthermore, employing single-cell sequencing technology, we delved into the cellular heterogeneity and metabolic pathway impacts of KHDRBS1 within the tumor microenvironment." (PMID 38660302, 2024). "This implies that KHDRBS1-positive HCC cells may modulate the HCC tumor microenvironment by affecting the functionality of SPP1." (PMID 38660302, 2024). "In this study, we evaluated whether the leptin/LEPR/KHDRBS1 axis, reported in the cellular model as relevant to tumour progression, could be expressed in bone metastatic tissue in vivo." (PMID 33213024, 2020). "The overlap with differentially expressed genes in tumor versus normal breast tissues identified a subset of 24 genes, 4 of which associated to the highest negative prognostic impact in BC (KHDRBS1, EXO1, CHEK1, BARD1)." (PMID 35217791, 2022). "Our data suggest that KHDRBS1 may have different functions in the two phases of tumour growth." (PMID 33213024, 2020). "Our study identifies KHDRBS1 as a tumor-promoting factor in HCC, with its positivity correlating with tumor progression." (PMID 38660302, 2024). "In this study, nude mice were divided into five groups to be respectively injected different GBM cells for verifying the roles of KHDRBS1, SNORD51 and ZBED6 in tumor growth." (PMID 39516455, 2024). "Specifically, the splicing machinery components KHDRBS1, NOVA1, PRPF8, SNW1, SRSF1, SRSF10 and SRSF9 were overexpressed in tumor tissue." (PMID 38049848, 2023). "Notably, KHDRBS1-deficint tumours displayed accelerated growth yet responded more robustly to F1F3 treatment, suggesting a context-dependent tumour-suppressive role of KHDRBS1." (PMID 40738927, 2025). "Notably, KHDRBS1 KO HeLa tumours exhibited accelerated growth in NSG mice, suggesting a potential tumour suppressor role of KHDRBS1 in immunodeficient contexts." (PMID 40738927, 2025). "The results showed that, compared with the PBS treated group, F1F3 significantly inhibited the growth of KHDRBS1 KO HeLa tumours, but not wild-type HeLa tumours." (PMID 40738927, 2025). "Finally, our in vivo study showed that the combination of KHDRBS1 knockdown, SNORD51 knockdown and ZBED6 overexpression significantly reduced the volume of the xenograft GBM tumor and prolonged the survival time of nude mice." (PMID 39516455, 2024). "Interestingly, 16 of the 34 components examined (47.1%) were altered and, in line with our Discovery cohort, KHDRBS1, NOVA1, PRPF8, SNW1, SRSF1, and SRSF9 were also overexpressed in tumor tissue in this external cohort." (PMID 38049848, 2023). "In this way, KHDRBS1 may play a role in amplifying the response of bone metastasis to leptin, which would underscore the relevance of the leptin/LEPR system in tumour progression." (PMID 33213024, 2020). "Additionally, our focus on KHDRBS1 expression in HCC reveals that its high expression correlates with higher disease differentiation, tumor grade, and vascular invasion, indicating its significant role in tumor invasiveness and progression." (PMID 38660302, 2024).
KHDRBS1 also shares sentences with these, for which no sentence is quoted: infection (8 papers); cervical cancer (6); Obesity (5); renal cell carcinoma (5); breast tumors (4); pancreatic cancer (4); acute myeloid leukemia (3); adenocarcinoma (3); Insulin resistance (3); spinal muscular atrophy (3); Arthritis (2); Ataxia (2); breast adenocarcinoma (2); colorectal tumors (2); diabetes (2); Ewing sarcoma (2); Hyperglycemia (2); Infertility (2); leukemia (2); lung carcinoma (2); ovarian carcinoma (2); renal carcinoma (2); rheumatoid arthritis (2); skin cancer (2); triple-negative breast carcinoma (2); Atrophy (1); autism (1); basal cell carcinoma (1); bladder cancer (1); colitis (1).
A further 28 diseases each share a sentence with KHDRBS1 in 1 paper.